DHODH (dihydroorotate dehydrogenase (quinone))
Diseases named in the same sentence as DHODH in open-access papers (continued):
Sharing a sentence is not in itself a finding about the gene and the disease.
myeloid leukemia (2 papers, 2019 to 2022). A clonal proliferation of myeloid cells and their precursors in the bone marrow, peripheral blood, and spleen. "We have previously reported that 5-aminoimidazole-4-carboxamide ribonucleoside (AICAr) and brequinar, a DHODH inhibitor, induced differentiation of myeloid leukemia by activating the ataxia telangiectasia and Rad3-related (ATR)/checkpoint kinase 1 (Chk1) via pyrimidine depletion." (PMID 35790845, 2022).
nasopharyngeal carcinoma (2 papers, 2023 to 2025). A carcinoma arising from the nasopharyngeal epithelium. "This suggests that DHODH inhibitors should be used with caution during radiotherapy in nasopharyngeal carcinoma patients." (PMID 36737723, 2023).
Obesity (2 papers, 2021 to 2025). Accumulation of substantial excess body fat. "First hints that DHODH inhibition might be particularly relevant for T1D treatment came from obesity and T2D studies." (PMID 40706797, 2025).
pancreatic ductal adenocarcinoma (2 papers, 2024). An infiltrating adenocarcinoma that arises from the epithelial cells of the pancreas. "We examined gene expression changes following transient or prolonged DHODH inhibition by culturing human pancreatic ductal adenocarcinoma cell lines S2–013 and CFPAC-1 in the presence of BQ at two different doses for 16 hours and for a two-week duration." (PMID 37066260, 2024). "We examined gene expression changes following transient or prolonged DHODH inhibition by culturing human pancreatic ductal adenocarcinoma cell lines S2-013 and CFPAC-1 in the presence of brequinar (BQ) at two different doses for 16 hr and for a 2-week duration." (PMID 38973593, 2024).
renal carcinoma (2 papers, 2018 to 2024). A carcinoma arising from the epithelium of the renal parenchyma or the renal pelvis. "Altogether, DHODH was found to be highly expressed in renal cancers (KIRC and KIRP) and was significantly associated with a better prognosis in patients with ccRCC." (PMID 38796629, 2024).
type 1 diabetes (2 papers, 2021 to 2025). "•DHODH inhibition delays disease development in type 1 diabetes (T1D) models." (PMID 40706797, 2025).
bladder cancer (1 paper, 2024). "Specifically, in the case of bladder cancer, the use of BQR@MLipo has been shown to effectively target and inhibit DHODH activity, leading to mitochondrial lipid peroxidation and subsequent induction of ferroptosis in bladder cancer cells." (PMID 38853203, 2024).
cutaneous squamous cell carcinoma (1 paper, 2026). "We have previously identified a pivotal role of DHODH in the initiation of cutaneous squamous cell carcinoma (cSCC), the second most common type of non-melanoma skin cancer." (PMID 42049699, 2026).
delirium (1 paper, 2025). A disorder characterized by confusion; inattentiveness; disorientation; illusions; hallucinations; agitation; and in some instances autonomic nervous system overactivity. "There were eight protective genes (DHODH,DHRS7B,TOP1MT,CASP8,GFM1,CPT1B,TK2,GPD2), and four genes (SCP2,DMPK,GSTK1,SIRT3) that increased delirium risk, as shown inFigure 2, withp = 0.05 (dotted line); and false discovery rate (FDR) < 0.05 (red asterisks)." (PMID 41330563, 2025).
Freeman-Sheldon syndrome (1 paper, 2013). A very rare, multiple congenital contractures syndrome characterized by a microstomia with a whistling appearance of the mouth, distinctive facies, club foot and joint contractures. "Considering only genes that contained variants in all cases, the VEST gene score ranked dihydroorotate dehydrogenase (DHODH) number 2 of 2253 genes in four cases of Miller syndrome, and myosin-3 (MYH3) number 2 of 2313 genes in three cases of Freeman Sheldon syndrome." (PMID 23819870, 2013).
Hyperglycemia (1 paper, 2021). An increased concentration of glucose in the blood. "In summary, this study suggests a model wherein DHODH inhibitors reduce mitochondrial respiration to a moderate extent, but perhaps sufficiently to promote glucose consumption by tissues and reduce hyperglycemia." (PMID 34113829, 2021).
lymph node metastasis (1 paper, 2021). "Further, DHODH expression was substantially enhanced in OSCC patient with lymph node metastasis (P = 0.046 4)." (PMID 33510132, 2021).
macular edema (1 paper, 2022). "DHODH-inhibition was shown to induce apoptosis in mast cells, which might explain the positive effect of KIO-100 (PP-001) on increased retinal thickness and macular edema, respectively, in addition to the suppression of T cells that fuel the inflammation by the activation of innate immune cells." (PMID 36325389, 2022).
mucormycosis (1 paper, 2023). "Building on this work, proteomes of the Mucorales were found to harbour only orthologs of class 1A DHODH; we pursued characterisation of enzymes from two representative species that are the most common etiological agents of mucormycosis." (PMID 37531380, 2023).
myeloid malignancies (1 paper, 2020). "The novel DHODH inhibitor BAY 240234 is currently under phase 1 clinical trial (NCT03404726) for myeloid malignancies, and preclinical data showed differentiative effects in several AML cell lines, including THP-1, and three subcutaneous AML xenografts in vivo." (PMID 33176741, 2020).
Myocardial fibrosis (1 paper, 2024). "When the FSP1 and/or GPX4 pathways were blocked, compared to when DHODH was not inhibited, inhibiting DHODH aggravated myocardial hypertrophy and myocardial fibrosis." (PMID 39737072, 2024). "DHODH inactivation alone did not weaken HDC’s effects in reducing Fe2+, alleviating myocardial hypertrophy, reducing myocardial fibrosis, and improving LVEF." (PMID 39737072, 2024).
osteosarcoma (1 paper, 2022). A usually aggressive malignant bone-forming mesenchymal neoplasm, predominantly affecting adolescents and young adults. "In conclusion, targeting GPX4, FSP1, GCH1, and DHODH has a great potential for combating osteosarcoma." (PMID 35402247, 2022). "Similarly, DHODH inhibitors are suggested to trigger ferroptosis through mitochondrial lipid peroxidation on those osteosarcoma cells with low GPX4 expression levels." (PMID 35402247, 2022).
papillary serous carcinoma (1 paper, 2023). "Uterine endometrial carcinoma is a common cancer subtype (83%) harboring an overexpression of DHODH compared with uterine serous carcinoma/papillary serous carcinoma (13%)." (PMID 38136273, 2023).
promyelocytic leukemia (1 paper, 2021). "Unlike differentiation, DHODH inhibition-induced apoptosis has not been thoroughly investigated; it has probably been considered a consequence of differentiation, somehow similarly to the effect induced by all-trans retinoic acid (ATRA) in promyelocytic leukemia (APL)." (PMID 33670894, 2021).
Respiratory tract infection (1 paper, 2013). An infection of the upper or lower respiratory tract. "This suggests that DHODH inhibitors should be further evaluated in vivo in the local treatment of respiratory tract infections." (PMID 24098125, 2013).
retinoblastoma (1 paper, 2024). A malignant tumor that originates in the nuclear layer of the retina. "We also show that DP on its own does not have any effect with regards to the proliferation/viability of retinoblastoma cells even a 10 μM, which is 10-fold the concentration used in the experiments combining DP with DHODH inhibitors." (PMID 38332874, 2024). "Cultured retinoblastoma cell lines were treated with small molecule inhibitors of DHODH alone or in combination with inhibitors of nucleoside uptake to also block the salvage pathway for pyrimidine ribonucleotide formation." (PMID 38332874, 2024). "To assess whether DHODH would be a target to consider in retinoblastoma, first we selected two of the most commonly studied retinoblastoma cell lines (Weri-Rb1 and Y79)." (PMID 38332874, 2024). "These two observations suggest that a wide range of retinoblastomas could be sensitive to low concentrations of DHODH inhibitors." (PMID 38332874, 2024). "Interestingly, 2 of the 102 retinoblastomas showed a homozygous deletion for DHODH, suggesting that these two cancers may respond to inhibitors of uridine transport on their own." (PMID 38332874, 2024).
soft tissue sarcoma (1 paper, 2023). A malignant neoplasm arising from muscle tissue, adipose tissue, blood vessels, fibrous tissue, or other supportive tissues excluding the bones. "As well as Ewing's sarcoma, synovial sarcoma is classified as a soft‐tissue sarcoma and is reported to be caused by a chromosomal abnormality, and thus it might be worth evaluating the effect of DHODH inhibitor on synovial sarcoma." (PMID 36825574, 2023).
uterine serous carcinoma (1 paper, 2023). "By contrast, uterine serous carcinoma has a predominate papillary pattern subtype that harbors a low expression of DHODH." (PMID 38136273, 2023).
cancer (138 papers, 2013 to 2026). A tumor composed of atypical neoplastic, often pleomorphic cells that invade other tissues. "The overexpression of dihydroorotate dehydrogenase (DHODH) in various malignant tumor cells is significantly associated with ferroptosis, making DHODH inhibition a promising strategy for cancer therapy." (PMID 41729981, 2026). "It has been revealed that high concentrations of BRQ induce mitochondria-associated ferroptosis in cancer cells, further substantiating the link between DHODH and mitochondrial-induced immune responses." (PMID 41144149, 2025). "Inhibition of DHODH has been associated with anti-proliferative effects, reduced metastasis, and increased apoptosis in various cancers." (PMID 40075750, 2025). "DHO protects cells from RSL3-induced ferroptosis, and the DHODH inhibitor brequinar (BRQ) is able to promote ferroptosis in GPX4-deficient cancer cells." (PMID 41293165, 2025). "Among the enzymes involved in de novo synthesis pathways, the expression and activity of DHODH are reported to be directly associated with cancer progression." (PMID 40804482, 2025). "Dihydroorotate dehydrogenase (DHODH), an enzyme involved in the de novo pyrimidine nucleotide synthesis pathway, has been specifically targeted in cancer cells with IDH mutations." (PMID 38921453, 2024). "Although DHODH is ubiquitously expressed in every human organ and has less than 4% mutation and alternation in cancer, malignant cells appear to be more metabolically dependent on de novo pyrimidine production." (PMID 39195509, 2024). "AOX expression can restore the growth of respiration-deficient cancer cells by allowing DHODH to function independently of CIII52,57." (PMID 37095097, 2023). "DHODH expression and enzymatic activity have been implicated in cancer progression in previous studies, but as a key enzyme in pyrimidine biosynthesis, DHODH has only recently become an attractive target for anticancer therapy." (PMID 36942513, 2023). "Inactivation of DHODH (knockout or inhibitor treatment) in cancer cells with low GPX4 expression causes severe mitochondrial lipid peroxidation and ferroptosis." (PMID 36429080, 2022). "Over half a century ago, the expression and enzymatic activity of DHODH were first associated with cancer progression, yet emerged only recently as a potential therapeutic target for cancer." (PMID 34145214, 2021). "DHODH might play an important role in cancer development and progression of cancer due to a severe proliferation defect associated with its deficiency." (PMID 41339932, 2025). "In particular, the mutational burden in DHODH overexpressing tumors likely provides a base for future researchers to test whether these cancer types respond to a class of cancer immunotherapy drugs." (PMID 38136273, 2023). "Our results also suggest that DHODH might be a potential prognosis marker for high-risk patients and/or an attractive therapeutic target for selected cancers." (PMID 38136273, 2023). "Based on the identified mutations, DHODH was classified as a candidate cancer driver." (PMID 34900699, 2021). "Moreover, the use of leflunomide to therapeutically target DHODH has been implicated under various cancer contexts as a metabolic inhibitor." (PMID 31841108, 2019). "Therefore, this study discovered that glutamine flux increased the sensitivity to DHODH suppression which leads to synthetic lethality in PTEN-deficient cells, and suggested DHODH could be a potential therapy for PTEN-deficient cancer patients." (PMID 37533462, 2023). "Our work introduces BCOR loss as a biomarker for DHODH therapy, relevant since BCOR mutations are poor prognostic markers in AML and other cancers." (PMID 41549155, 2026). "Conversely, in fields like cancer therapy, inhibiting DHODH is being explored as a strategy to enhance ferroptosis in cancer cells and improve chemotherapy efficacy." (PMID 41602830, 2026).
cancer (continued). "Overall, these findings indicate that cancer cells with compromised mitochondrial function readily acquire mtDNA from other cells in the tumor microenvironment to restore DHODH-dependent respiration and de novo pyrimidine synthesis." (PMID 41248423, 2026). "Recent experiments reported that inhibition of DHODH expression in mouse cancer cells inhibited the growth of tumors in immune competent mice, but not in immune-deficient NSG mice." (PMID 41339932, 2025). "DHODH is a critical component for pyrimidine synthesis, thereby enhancing the ability of cancer cells to engage in oxidative phosphorylation." (PMID 40289989, 2025). "Intriguingly, the expression of GPD2 (and also AIFM2, which encodes FSP1) showed a mutually exclusive expression pattern, whereas DHODH showed a positive correlation with LDHB in a large collection of cancer cell lines." (PMID 40090955, 2025). "Among the various metabolic pathways co-opted by cancer cells, de novo pyrimidine biosynthesis—principally regulated by the mitochondrial enzyme DHODH—has emerged as a tractable metabolic vulnerability." (PMID 41239499, 2025). "Suppressing DHODH led to pyroptosis in cancer cells and activated the cyclic GMP-AMP synthase (cGAS)-stimulator of interferon genes (STING) pathway, forming the basis for NK cell-induced anti-tumor immune responses." (PMID 41144149, 2025). "The de novo pyrimidine biosynthesis pathway is regulated by several enzymes, such as DHODH, that can be pharmacologically targeted, presenting therapeutic opportunities in cancers with dependency on this pathway." (PMID 40961924, 2025). "Inhibiting DHODH has been proposed as a potential strategy to counteract ferroptosis resistance in cancer cells." (PMID 40715045, 2025). "For example, studies have shown that inhibition of DHODH leads to effective growth suppression in certain types of cancers, including isocitrate dehydrogenase mutant glioma, diffuse midline glioma, and a KRAS-driven PDAC model." (PMID 41243973, 2025). "DHODH inhibition using small molecule drugs is effective for the treatment of preclinical cancer models such as small cell lung cancer, MYC-amplified medulloblastoma, and IDH1 mutant glioma." (PMID 40519286, 2025). "The rationale for combining both PDE7A and DHODH inhibitors is supported by previous studies in which targeting multiple nodes of the same cancer driver pathway has been shown to achieve better clinical outcomes." (PMID 40961924, 2025). "There is potential for DHODH inhibitors in cancer treatment, as DHODH has a central role in sustaining cancer cell proliferation and regulating anti-cancer immune activity." (PMID 40519286, 2025). "Given its role in cellular proliferation, DHODH is emerging as a promising therapeutic target in cancer." (PMID 40715045, 2025). "TCGA pan-cancer dataset was used to analyze DHODH expression in different cancer types and TCGA ccRCC dataset was used to assess differential expression, prognosis correlation, immune infiltration, single-gene, and functional enrichment due to DHODH." (PMID 38796629, 2024). "DHODH inhibitors have shown robust preclinical anticancer activity across diverse cancer types 5–14 and have recently entered clinical trials for multiple hematologic cancers (NCT04609826 and NCT02509052)." (PMID 37066260, 2024). "To search for therapeutic vulnerabilities induced by DHODH inhibition, we examined gene expression changes in cancer cells treated with the potent and selective DHODH inhibitor brequinar (BQ)." (PMID 37066260, 2024). "Previous research has established that DHODH inhibitors can be utilized in the treatment of cancer and a variety of immune-related diseases." (PMID 39452938, 2024). "Correspondingly, the inactivation or deletion of DHODH or GPD2 leads to heightened ferroptosis sensitivity in cancer cells due to the decreased production of CoQH2 within the mitochondria." (PMID 38428031, 2024).